ZNF527 (zinc finger protein 527)
Description:
May be involved in transcriptional regulation.
Synonyms: KIAA1829
Tractability: PROTAC: ubiquitination databases record sites on it.
Gene: Protein-coding gene on chromosome 19 (37,371,061 to 37,393,066, forward strand). Ensembl gene ENSG00000189164.
Subcellular location: Nucleus
Subcellular location (Human Protein Atlas): Nuclear speckles; Golgi apparatus
Gene Ontology:
Molecular function: DNA-binding transcription factor activity, RNA polymerase II-specific; RNA polymerase II cis-regulatory region sequence-specific DNA binding
Biological process: regulation of transcription by RNA polymerase II; regulation of DNA-templated transcription
Cellular component: nucleus
Genetic constraint (gnomAD): Loss-of-function variants: 6 observed, 15.48 expected, observed/expected ratio (o/e) 0.39, 90% interval 0.21 to 0.76. The upper end of that interval is the gene's LOEUF score, 0.76, which puts it in group 3 of 6, group 1 being the genes least tolerant of losing a copy. Missense variants: 626 observed, 762.69 expected, observed/expected ratio (o/e) 0.82, 90% interval 0.77 to 0.88. Synonymous variants: 209 observed, 257.06 expected, observed/expected ratio (o/e) 0.81, 90% interval 0.73 to 0.91.
Homologues: Orthologues: chimpanzee ZNF527 (99% identical), macaque ZNF527 (97% identical), pig ZNF527 (89% identical), rabbit ZNF527 (82% identical), guinea pig ZNF527 (78% identical). Paralogues in human: ZNF287 (40% identical), ZKSCAN7 (38% identical), ZNF214 (38% identical), ZNF852 (38% identical), ZNF34 (37% identical), ZNF17 (34% identical), ZNF530 (34% identical), ZNF136 (33% identical), ZNF627 (33% identical), ZNF285 (33% identical), ZNF333 (33% identical), ZNF416 (33% identical), and 38 more.
Diseases named in the same sentence as ZNF527 in open-access papers:
ZNF527 is named in the same sentence as 1 disease in open-access papers, as found by Europe PMC text mining. Sharing a sentence is not in itself a finding about the gene and the disease. The quoted sentences say what the papers report.
viral infection (1 paper, 2025). "Although direct evidence for ZNF527 in viral infection remains limited, zinc finger protein family members typically participate in antiviral immune responses." (PMID 41471859, 2025). "We identified 31 differentially expressed circRNAs and 7 mRNAs (HSPA8, HSPA1B, EGR2, CXCR4, SOCS3, NOTCH3, and ZNF527) related to viral infection." (PMID 41471859, 2025).